TNF (tumor necrosis factor)
Diseases named in the same sentence as TNF in open-access papers (continued):
Sharing a sentence is not in itself a finding about the gene and the disease.
Insulin resistance (continued). "Both insulin resistance in type 2 diabetes and immune mediated destruction of pancreatic β cells in type 1 diabetes produce proinflammatory cytokines, such as tumor necrosis factor α and interleukin-6." (PMID 38555533, 2024). "TNF-α, ChAs, and growth hormones induce insulin resistance by inhibiting tyrosine kinases and the tyrosine phosphorylation of IRS-1." (PMID 39682557, 2024). "The insulin resistance model (TNF-a and TNF-a+INS) showed an opposite behavior, i.e., a significant decrease of p-Akt and a significant increase of p-JNK." (PMID 39627194, 2024). "Proinflammatory cytokines, such as interleukin-6 (IL-6, IL-1) and tumor necrosis factor-α (TNF-α) play significant roles in the development of insulin resistance and hyperglycemia in trauma patients." (PMID 39682557, 2024). "In these studies, obese rodents and human adipose tissue have demonstrated higher levels of pro‐inflammatory cytokines such as TNF‐α, which can promote insulin resistance by inactivating the IRS‐1 molecule." (PMID 37329278, 2023). "In ob/ob mice, deletion of TNFα or obesogenic diet leads to a reduction in insulin resistance and improvement in insulin signaling in the WAT and muscles." (PMID 37755259, 2023). "During the treatment, the inflammatory factors high-sensitivity C-reactive protein (hsCRP), adiponectin, and TNF-α, which are normally related to insulin resistance, were all decreased." (PMID 36677959, 2023). "Resistin induces the synthesis of pro-inflammatory cytokines, such as tumor necrosis factor α (TNF α) and IL-6, and also promotes insulin resistance, mainly in hepatocytes, by activating gluconeogenesis enzymes and enhancing glycogenolysis." (PMID 36978817, 2023). "The release of proinflammatory cytokines, such as tumor necrosis factor-α (TNFα), from AT, is increased in obese patients or patients with insulin resistance, which seems to play a crucial role in liver steatosis, inflammation and fibrosis." (PMID 36768637, 2023). "For example, TNF-α/tumor necrosis factor receptor 1 (TNFR1)/IRS-1 signaling is one of the most important regulatory axes for insulin resistance." (PMID 37555019, 2023). "Studies have shown that decreased levels of adiponectin and increased levels of inflammatory cytokines like IL-6, and TNFα contribute directly to insulin resistance and also directly prevent adiponectin secretion from adipocytes." (PMID 37013538, 2023). "Central obesity, which forms the basis of insulin resistance and the metabolic syndrome, results in the production of pro-inflammatory cytokines such as tumor necrosis factor alpha (TNF-α) and interleukin-6 (IL-6)." (PMID 36830898, 2023). "It has been demonstrated that TNF-α leads to insulin resistance and contributes to β-cell destruction." (PMID 37180128, 2023). "Tumor necrosis factor alpha (TNFα) is a proinflammatory cytokine typically induced in adipose tissue in conditions of insulin resistance and Type 2 diabetes." (PMID 37237488, 2023). "It is associated with elevated inflammatory markers, such as C-reactive protein, interleukin 6 (IL-6) and tumor necrosis factor (TNF), which can increase insulin resistance." (PMID 36810280, 2023). "A possible reduction in insulin resistance with anti-TNF therapy was reported in a meta-analysis of 12 studies; however, the heterogeneity of the studies was high." (PMID 37763669, 2023). "Genistein suppresses NF-κB activation, reduces TNF-α and IL-6 production, and reactivates insulin-mediated Akt and endothelial NO synthase phosphorylation to improve insulin resistance-related endothelial dysfunction." (PMID 37229273, 2023). "Further, anthocyanins improved inflammation induced by TNF-α and insulin resistance in adipocytes by activating insulin signaling and enhanced translocation of GLUT4." (PMID 38005786, 2023). "TNF induces insulin resistance in adipocytes by inhibiting insulin-induced IRS1 tyrosine phosphorylation and insulin-induced glucose uptake." (PMID 36818229, 2023).
Insulin resistance (continued). "In the presence of insulin resistance, proinflammatory cytokines such as TNF-α, monocyte chemotactic protein-1 (MCP-1), C-reactive protein (CRP), and interleukins are increased." (PMID 36834911, 2023). "Proinflammatory cytokine TNFα can activate intracellular inflammatory signaling, leading to insulin resistance and glucose intolerance." (PMID 38057733, 2023). "Inadequate secretion of cytokines such as TNF-α and IL-10 strengthens insulin resistance in db/db mice, resulting in adipocytes’ increased insensitivity to insulin." (PMID 38202328, 2023). "Published literature indicates that the role of tumor necrosis factor in the development of insulin resistance is well established, but the mechanism of interaction in humans has not yet been reported." (PMID 37063831, 2023). "In contrast, when collagen deposition is normalized by either reduction of mitochondrial oxidative stress or inhibition of phosphodiesterase (PDE) 5a, expression of TNF-α and F4/80 in skeletal muscle is normalized and insulin resistance in mice is improved." (PMID 37383542, 2023). "Several reports have revealed that inflammatory molecules such as interleukin 6 (IL-6), tumor necrosis factor-α (TNF-α), and C-reactive protein (CRP) are elevated in individuals with T2DM and associated with insulin resistance." (PMID 37445656, 2023). "Further, some studies have shown that insulin resistance in patients with psoriasis is improved after the introduction of TNF inhibitors." (PMID 37109438, 2023). "On the contrary, pro-inflammatory cytokines from adipose tissue, such as TNF-α, IL-6, and MCP-1, are known to be associated with insulin resistance." (PMID 36834930, 2023). "Dual infection with HIV-1 and hepatitis C (see also the section about hepatitis below) virus results in an increase in TNF-α and steatosis which together induce insulin resistance." (PMID 36768699, 2023). "Simultaneously, increased levels of adipokines and inflammatory cytokines (such as IL-1, IL-6 and TNF-α) activate NF-κB signaling pathway and promote insulin resistance." (PMID 37424859, 2023). "Increases in cellular responses enhance secretion of TNF-α by macrophage, NK cells and lymphocytes promoting insulin resistance on a cellular level, a pyrogenic response and enhanced inflammation." (PMID 37923927, 2023). "On the one hand, arthritis is known to cause the upregulation of proinflammatory cytokines, such as tumor necrosis factor (TNF) and interleukin (IL), which are closely associated with insulin resistance." (PMID 37608322, 2023). "More specifically, excessive TNF-alpha promotes skeletal muscle insulin resistance by negatively regulating insulin signal transduction to glucose uptake." (PMID 37139450, 2023). "Previous studies have shown that obese individuals have elevated IL-1β and TNF-α levels, which can induce insulin resistance, promote FFA production, and affect glucose and lipid metabolism." (PMID 37693249, 2023). "Autophagy-related DEGs are linked to autophagy, apoptosis, NOD-like receptor signaling, TNF signaling, and the insulin resistance pathway." (PMID 38002949, 2023). "The GM changes result in the reduction in TNF-α and IL-10, which reduces inflammation and insulin resistance." (PMID 36904222, 2023). "In this study, the inflammatory factors TNF‐α and IL‐1 β decreased significantly, insulin secretion decreased, insulin resistance symptoms alleviated, and the level of HOMA‐β increased in each intervention group." (PMID 37181308, 2023). "It was also demonstrated that the liver adipose tissue secretes several proinflammatory factors, such as interleukin 6 (IL-6) and tumor necrosis factor alpha (TNF-α), which play a role in inducing systemic insulin resistance." (PMID 36834741, 2023). "Several pro-inflammatory cytokines, such as the C-reactive protein (CRP), tumor necrosis factor-α (TNF-α) and interleukin-6 (IL-6), have been unequivocally shown to promote both insulin resistance (IR) and atherogenesis." (PMID 36900073, 2023).
Insulin resistance (continued). "Interleukin-6 (IL-6), Interleukin 1-β (IL1-β), and tumor necrosis factor α (TNFα) increase local and systemic inflammation, recruit macrophages, and alter insulin signaling to promote insulin resistance." (PMID 37443781, 2023). "In 3T3-L1 adipocytes, a study found that C3G treatment effectively reverted the insulin resistance induced by H2O2- or TNF-α via the downregulation of the c-Jun N-terminal kinases (JNK) signaling pathway." (PMID 38005786, 2023). "Studies have shown that TNF-α participates in insulin resistance and ROS production through the regulation of glucolipotoxicity pathways." (PMID 37005639, 2023). "In obesity, the increased levels of proinflammatory cytokines, such as IL-1β, IL-6, TNF-α and MCP1, in adipose tissues area direct cause of insulin resistance." (PMID 38066566, 2023). "Muscle fibers also influence the immunological response by controlling interleukin-6 and other peptides, regulating the synthesis of tumor necrosis factor-alpha and insulin resistance." (PMID 37592262, 2023). "Key players that were found to be involved in insulin resistance are inflammatory cytokines like TNFα, IL-6, C-reactive protein and plasminogen activator inhibitor, all of which were found to be elevated in obese mice." (PMID 38137918, 2023). "Tumor necrosis factor-alpha (TNF-α), released by monocytes, has been associated with insulin resistance in PCOS." (PMID 38189053, 2023). "According to studies, high TNF-α levels and hypoadiponectinemia both contribute to insulin resistance." (PMID 37009872, 2023). "The adipose tissue TNFα acts in a paracrine manner on adipocytes and contributes to the development of insulin resistance through the induction of lipolysis, impairment in insulin signaling, and alterations in gene and protein expression." (PMID 37237488, 2023). "TNF-α is an important cytokine involved in metabolic diseases such as obesity, insulin resistance, hyperlipidemia, and NAFLD." (PMID 37298268, 2023). "High levels of tumor necrosis factor-α (TNF-α) in the adipose tissue of obese mice resulted in insulin resistance by inhibiting peroxisome-proliferator-activated receptor γ function." (PMID 37108143, 2023). "miR-146a expression was shown to be negatively correlated with glycated hemoglobin, insulin resistance, NF-κB mRNA levels and circulating levels of TNFα as well as IL-6." (PMID 37629307, 2023). "This in turn triggers pro-inflammatory macrophage aggregation, Treg cell reduction, and IL-6 and TNF-α secretion increases, leading to systemic inflammation, insulin resistance, oxidative stress, and a series of metabolic reactions." (PMID 36843589, 2023). "It is known that in insulin resistance, there is an increase in pro-inflammatory cytokines such as interleukin (IL)-1, IL-6, and tumor necrosis factor (TNF)-α." (PMID 37629193, 2023). "Increased levels of inflammatory cytokines such as tumor necrosis factor (TNF) are linked to HIV lipodystrophy, and these cytokines have a role in insulin resistance, poor glucose tolerance, and perhaps the development of diabetes." (PMID 37746464, 2023). "A high-fat diet induced hepatic insulin resistance and marked increases in plasma TNFα (eight-fold) and IL-6 (60%) in apo-CIII-overexpressing mice." (PMID 37895151, 2023). "The adipose tissue is the biggest endocrine organ producing proinflammatory cytokines (tumor necrosis factor α (TNF-α), IL-6, IL-17) and adipokines which are involved in dyslipidemia, insulin resistance (IR), diabetes, and feather CVD development." (PMID 37762217, 2023). "TNF-α can lead to increased gluconeogenesis and impaired glucose utilization in peripheral tissues, and can also induce insulin resistance in tumour patients." (PMID 37533569, 2023). "Adiponectin has hepatoprotective effects due to its ability to reduce inflammation, inhibiting the release of proinflammatory cytokines such as IL-6 and TNF-α and improving insulin resistance." (PMID 37998747, 2023).
Insulin resistance (continued). "Individuals that are overweight and implemented a KD also had decreased body weight, insulin resistance, and serum markers of inflammation (e.g., TNF-α, IL-6, IL-8, MCP-1)." (PMID 36937529, 2023). "The mechanisms started with PAKs or metabolic excess including TNF-α, endothelin-1, FFA or ER stress which exhibit ser/Thr phosphorylation of insulin receptor substrate 1(IRS1) and cause insulin resistance." (PMID 37014444, 2023). "The impaired synthesis of adipose tissue hormones such as leptin, adiponectin, visfatin, and tumor necrosis factor-α (TNF-α) is linked to the onset of atherosclerosis, type 2 diabetes, and insulin resistance." (PMID 37375800, 2023). "There exist multiple direct and indirect pathways through which TNF-α can bring about insulin resistance." (PMID 38132485, 2023). "It interacts with inflammatory signaling pathways, such as NF-κB and JNK, regulating the production of pro-inflammatory cytokines like TNF-α and IL-6, which contribute to chronic inflammation and insulin resistance." (PMID 37605113, 2023). "FGF21 is a hormone that regulates glucose and lipid metabolism, while IL-6 and TNF-α are proinflammatory cytokines that play a role in insulin resistance." (PMID 37238961, 2023). "It has been suggested that Il-6 and TNF-alpha are involved in the pathogenesis of insulin resistance and type 2 diabetes by inhibiting insulin receptor tyrosine phosphorylation and reducing insulin production in pancreatic beta cells." (PMID 37509592, 2023). "Increased permeability in the intestinal epithelium induces metabolic endotoxemia, insulin resistance, and inflammation and fibrosis in the liver through TNF-α production." (PMID 36768946, 2023). "Decreased SIRT1 contributed to TNF-α-induced insulin resistance in skeletal muscle of patients with type 2 diabetes." (PMID 37108143, 2023). "In the obesity state, adipose tissue releases various proinflammatory cytokines, such as TNF‐α and IL‐6, and adipokines, such as resistin and leptin, which promote pathways affecting insulin resistance." (PMID 37329278, 2023). "IL-1, TNF-α, C-reactive protein (CRP), and monocyte chemoattractant protein-1 (MCP-1) are associated with skeletal muscle insulin resistance." (PMID 37876013, 2023). "On its hand, IL-1β further promotes insulin resistance, triggering TNF-α production and decreasing the phosphorylation of IRS-1, also contributing to β-cell failure and diabetes progression." (PMID 37299482, 2023). "Insulin resistance results in reduced glucose uptake by impairing insulin signaling, which is consistent with our results; that is, LPS, TNFα, and IFNγ (LTI) treatment markedly suppresses glucose uptake and Akt activation." (PMID 36771210, 2023). "It has been demonstrated that inflammatory factors, including IL-1, TNF-α, CRP, and MCP-1, are linked to tissue insulin resistance, and this relationship is mediated by the JNK and NF-кB pathways." (PMID 37876013, 2023). "Under obese conditions, however, adipocytes enlarge and change their shapes and produce TNF-α, thereby inducing inflammation, insulin resistance, and diabetes." (PMID 36768946, 2023). "In the liver, TNF induces numerous biological responses such as insulin resistance, liver inflammation and hepatocyte apoptosis and necroptosis, which further interconnects inflammation with metabolic signals." (PMID 37764698, 2023). "This is because the levels of TNF-α messenger ribonucleic acid (mRNA) and the production of TNF-α in human skeletal muscle are raised in patients with type 2 diabetes or insulin resistance." (PMID 37107955, 2023). "Proinflammatory mediators such as TNF-α, IL-6, and IL-1β played pivotal roles in the development of insulin resistance in adipose tissue of HFD-fed obese mice." (PMID 37111032, 2023). "Hyperglycemia-induced AGE/RAGE, ROS, and HbA1c activated apoptosis in the nerve fibers and insulin resistance via the activation of NFκB and the release of TNF-α." (PMID 38067127, 2023).
Insulin resistance (continued). "The suppression of GLUT4 synthesis arising from the increased production of TNF-α in muscle cells induces insulin resistance and diabetes." (PMID 36768946, 2023). "Circulating pro-inflammatory cytokines, such as IL-6 and TNF-α, can be promoted by TG deposition in adipose tissue; in turn, the amplifying inflammatory signal contributes to further adiposity and insulin resistance." (PMID 38201888, 2023). "Then the macrophages and adipocytes secrete TNF-α, IL-6, and other inflammatory factors, which lead to insulin resistance, insulin secretion dysfunction, and metabolic syndrome." (PMID 37072819, 2023). "In another study, exosome-like vesicles from murine adipose tissue were shown to similarly induce insulin resistance by motivating the upregulation of tumor necrosis factor alpha (TNF-α) and IL-6." (PMID 37745252, 2023). "High levels of inflammatory biomarkers, such as tumor necrosis factor-α (TNF-α) and interleukine-6 (IL-6), are associated with insulin resistance, a frequent disturbance in this syndrome." (PMID 36817281, 2023). "TNF-α is an inflammatory protein synthesised by immune and adipose cells and promotes insulin resistance by alterations in the insulin receptor signaling pathway." (PMID 37215211, 2023). "M1 macrophage accumulation in adipose tissue will produce various pro-inflammatory cytokines and chemokines that contribute to insulin resistance, such as tumor necrosis factor-alpha (TNF-α), interleukin 6 (IL-6), resistin, and leptin." (PMID 37104164, 2023). "M1 macrophages secrete an increasing number of pro‐inflammatory cytokines such as TNF‐α, interleukin (IL)‐1β, and IL‐23, which are critically involved in insulin resistance and T2DM." (PMID 37329278, 2023). "Animals exposed to TNF-α for extended periods of time developed insulin resistance; conversely, TNF-α neutralization improved insulin sensitivity." (PMID 38132485, 2023). "It seemed that different factors were responsible for the MPV increase in NASH subjects with liver fibrosis, such as insulin resistance and AT-related proinflammatory cytokines (including IL-1β, IL-6 and TNFα)." (PMID 36768637, 2023). "TNF-α can stimulate serine phosphorylation of the insulin receptor, which leads to insulin resistance." (PMID 36788534, 2023). "Increased TNF‐α levels impair insulin signalling through serine phosphorylation, which induces insulin resistance and leads to the development of T2DM." (PMID 37257051, 2023). "Inflammation and cholinergic dysfunction are targeted through PI3K/Akt, neurotrophic factor (NTF), Hypoxia-inducible factor 1 (HIF-1), mTOR, TNF and insulin resistance (IR) signalling pathways." (PMID 36978911, 2023). "A high-fat diet has been shown to induce a TNF-dependent increase in circulating inflammatory monocytes that predicts increased blood insulin levels and insulin resistance." (PMID 37569635, 2023). "Serum levels of this neuropeptide positively correlate with insulin resistance and obesity, and inflammation (particularly by TNF-α production) and oxidative stress have been proposed as the link between apelin/APJ and insulin resistance." (PMID 36902176, 2023). "Palmitate, for example, as a saturated fatty acid, promotes cytokines secretion as IL-6 and TNF-α that can lead to insulin resistance and glucose intolerance." (PMID 36677559, 2023). "In support of this, infusion of the pro-inflammatory cytokine TNF-α in healthy humans has been shown to trigger insulin resistance." (PMID 37049621, 2023). "In the early stages of MAFLD, macrophages secrete pro-inflammatory cytokines such as TNF-α and IL-6, which contribute to liver injury and promote the development of insulin resistance." (PMID 37361209, 2023). "A possible reduction in insulin resistance with anti-TNF therapy was reported in a meta-analysis of 12 studies." (PMID 37763669, 2023).